CD274 (CD274 molecule)
Diseases named in the same sentence as CD274 in open-access papers (continued):
Sharing a sentence is not in itself a finding about the gene and the disease.
tumor (continued). "Chemotherapy, PARPi and radiotherapy, as monotherapies or combined, might either enhance cytotoxic T lymphocytes against tumor cells or induce immunosuppressive effects through up-regulation of PD-L1 (also known as CD274)." (PMID 33804458, 2021). "Immune checkpoint inhibitors were administered to 26% of the matched patients (N = 14) based upon a ≥ 1% positive tumor cell (equals “low”) expression of PD-L1 by IHC and/or PD-L1 (CD274) amplification (N = 11), TMB-high/intermediate (N = 8), and/or MSI-high (N = 1)." (PMID 34607609, 2021). "This increase is reflected by significantly increased expression of CD274 in the tumor." (PMID 33796222, 2021). "To predict the sensitivity to ICIs between low- and high-risk groups as classified by the GDPLichi model, we further examined immunotherapy-related markers such as tumor mutation burden (TMB), neoantigen, and expression of PDCD1 (PD-1), CD274 (PD-L1), and CTLA4." (PMID 34970479, 2021). "The IL2RB-biased engineered cytokine NKTR-214 significantly increases the ratio of CD8 CTLs to immunosuppressive CD4 FOXP3 T-regulatory cells, creating a potent anti-tumor environment, while also increasing the expression of immune-checkpoints such as CD274 (PDL1)." (PMID 33928242, 2021). "The positive correlation of the risk score with the expression levels of PDL1 (CD274), PDCD1, and CTLA4 was found, suggesting that metabolic reprogramming genes may have a significant effect on the tumor immune microenvironment." (PMID 33413205, 2021). "CD274 is a key molecule of tumor immune checkpoint mechanisms, is one of the main targets of immunotherapy, and plays an important role in tumor immune escape." (PMID 35280928, 2021). "Importantly, POLD1 expression was associated with immune checkpoint molecules, including CD274, CD80, CD86, CTLA4, PDCD1 and TCGIT, and facilitated an immune-excluded tumor microenvironment." (PMID 34868924, 2021). "CD274 (PD-LI) is one of the most well-known biomarkers for tumor immunological therapy." (PMID 32201516, 2020). "PD-L1 (CD274/B7-H1, a transmembrane protein) is an anti-apoptotic factor for tumour cells resulting in resistance to cytolysis by CTLs and drug-induced apoptosis, and engagement of PD-L1 with its receptor PD-1 on T-cells additionally triggers apoptosis of CTLs." (PMID 32937961, 2020). "The inflamed TME was characterized by higher expression of PDCD1, CTLA4, CD28, (PD-L1) CD274, PD-L2, and lower tumor mutation burden than non-inflamed TME." (PMID 32528935, 2020). "Recently, miR-195 and miR-497 were found to downregulate the cluster of differentiation CD274 (also known as PD-L1) in triple negative breast cancer cells, suggesting that miR-195/miR-497 influence tumor progression, inhibit the immune response and promote tumor immune escape." (PMID 32316552, 2020). "Since many tumors can express PD-L1/CD274, the rationale of the PD-L1 pathway blockade is to inhibit the immunosuppressive PD-L1/PD1 interaction between tumor cells and T cells that hampers the activity of CD4+ and CD8+ T cells thereby enhancing T cell-mediated antitumor activities." (PMID 33066260, 2020). "PD-L1/CD274 expression in tumor tissues has emerged as one such candidate biomarker of therapy response, since patients with PD-L1/CD274-expressing advanced tumors have a higher objective response rate and improved PFS and OS as compared to the negative subgroups." (PMID 33066260, 2020). "The Programmed cell death ligand 1 (PD-L1 or CD274) gene encodes an immune inhibitory receptor ligand that is expressed by hematopoietic and non-hematopoietic cells, such as T cells, B cells, and various types of tumor cells." (PMID 32695218, 2020). "Prediction of the anti-PD-1 treatment response showed that SCE_H is more sensitive to anti-PD-1 than other subtypes, indicating that CD274 is highly expressed in tumor/tumor stem cells and may be involved in the tumor immune escape process." (PMID 33115513, 2020).
tumor (continued). "We injected bEnd.3 (−) or CD274-bEnd.3 (+) cells into tumor tissues separately, and found that the tumor tissues with bEnd.3 (+) group (injected intratumorally CD274-bEnd.3 (+)) had a faster growth rate compared to the bEnd.3 (−) group (injected intratumorally bEnd.3 (−))." (PMID 32366856, 2020). "Predicted CD274 gene expression in tumor-infiltrating macrophages in different tumor types." (PMID 32520957, 2020). "CD274 (PD-L1), exploited by tumors to attenuate anti-tumor immunity, was strongly upregulated in the tumor (log2 ratio, 4.1), suggesting that anti-PD-1/PD-L1 therapy might be sufficient for this patient." (PMID 32702887, 2020). "Across 33 tumor types, CD274 and CD8A had broader positive correlations with m6A regulators." (PMID 33585244, 2020). "Antitumor immune response-enhancing transcription factor Forkhead box O (FoxO) inhibits CD274 expression, suggesting that CD274 expression may be responsible via reverse signaling for hiding immune response-enhancing features of tumor cells." (PMID 31824480, 2019). "In addition, our results of the longitudinal samples showed the increased expression of PDCD1 and CD274 only in the post-trastuzumab tumor, supporting the notion that PD-1 expression is an indicator of trastuzumab response." (PMID 31618954, 2019). "Similarly, the four mouse tumor cells had CD274+ cells with expression rates of 67.4%, 68.0%, 70.0% and 70.0%, respectively, comparison to isotype control." (PMID 30872703, 2019). "The high-expression of CD47 and CD274 on cancer surface may be the reason why circulating tumor cells could escape from the immune system." (PMID 30872703, 2019). "Blocking both CD47 and CD274 may be a good method for treatment of tumor metastasis, and at the same time this could be a solution to the limitations of single antibody limitation, fewer checkpoints and poor targeting." (PMID 30872703, 2019). "PD-L1, also known as B7-H, B7H1, PDL1, PDCD1L1 or PDCD1LG1, is an immune inhibitory receptor ligand expressed by hematopoietic and non-hematopoietic cells, such as T-cells and B-cells and many types of tumor cells, that in humans is encoded by the CD274 gene." (PMID 31075880, 2019). "CD274-L2a-derived soluble PD-L1 delays in vivo tumour growth." (PMID 31729316, 2019). "In addition to H3K9me3, verticillin A also targets H3K4me3 in pancreatic cancer cells, as treatment of tumor-bearing mice decreased the H3K4me3 levels in the cd274 promoter region in the orthotopic tumor tissues." (PMID 31569621, 2019). "In the anti-CD47 or anti-CD274 treated group, tumor nodules were reduced in the lungs." (PMID 30872703, 2019). "The antibodies could effectively block the expressions of CD47 and CD274 on the cell surface and stably attached to tumor cell surface for several hours." (PMID 30872703, 2019). "Tumor CD274 expression is a potential biomarker of a better response to anti-PDCD1/CD274 therapies." (PMID 29361689, 2018). "In particular, neither assessing intratumoral expression levels of CD274 (best known as PD-L1) by immunohistochemistry, nor evaluating tumor mutational burden by whole-exome sequencing appears to suffice to predict long-term clinical benefits." (PMID 29743104, 2018). "The proximal promoter region of CD274 (PD-L1) was sequenced in all cultured tumor lines." (PMID 30400822, 2018). "Programmed death-ligand 1 (PD-L1 or CD274) engaged by PD-1 in cancer cells could inhibit the self-reactivation of T cells and induce tumor immune tolerance." (PMID 28881642, 2017). "Hypothetically, CD274 (PD-L1) was involved in immune-suppression and might be overexpressed in “worse prognostic group” and possibly resistant to anti-tumor therapy." (PMID 29108360, 2017). "Moreover, we identified the immune checkpoint PD-L1 (CD274) as a novel miR-93/106b target playing a central role in diminishing tumor immunity." (PMID 28423491, 2017).
tumor (continued). "Therefore, we can suggest that CD274(PD-L1) expression in tumor stroma would influence on immune reaction in the setting of preoperative chemoradiotherapy." (PMID 29108360, 2017). "Furthermore, CD274 (i.e. PD-L1) was significantly up-regulated in most of the tumours but downregulated in only two tumours." (PMID 28886030, 2017). "Treatment of adoptively transferred CLL tumor cells with either recombinant PD-1 or anti-CD274 resulted in a significant reduction of transferred tumor cells at both 2- and 24-h time points in peripheral blood (both time points), as well as in the spleen, lymph nodes, and lungs (24-h time point)." (PMID 28512625, 2017). "Taken together, NNMT, FLI1, GAS6, lncRNA CCAT1, PDCD1LG2, and CD274, whose differential expression was confirmed, may be involved in the major mechanism of tumor-like transformation induced by chronic P. gingivalis infection." (PMID 28286742, 2017). "However, tumours have evolved other means to suppress immune attack such as by upregulating T-cell co-inhibitory molecules, typified by Programmed death-ligand (PD-L1, a.k.a., CD274), on the cancer cell surface." (PMID 28198370, 2017). "Programmed cell death protein 1 (PD-1, encoded by PDCD1 gene) and one of its two known ligands, the programmed death ligand-1 (PD-L1, encoded by CD274 gene) are among the therapeutically most important checkpoint proteins that mediate tumor-induced immune suppression through T-cell downregulation." (PMID 27861596, 2016). "Furthermore, CD274/PD-L1 was upregulated in DEV tumor cells after coculture with T cells or monocytes and its expression was validated in 12/19 cases of LP-DLBCL." (PMID 27708232, 2016). "Tumour transcriptional analysis demonstrated that, as a rapid and early consequence of vaccination, several profoundly immunosuppressive genes were highly upregulated, including CD274 (PD-L1), LGALS9 (Galectin-9), TGFβ1, LAG3 and HAVCR2 (TIM-3)." (PMID 26861383, 2016). "Lymph node-residing CLL cells, which have been shown to comprise activated, proliferating tumour cells with high expression of costimulatory and adhesion molecules, would thus be protected from T cell-mediated cytolysis by expressing CD274." (PMID 25940792, 2015). "Furthermore previous studies have demonstrated the presence of PD1 expression on infiltrating T-cell populations and PD-L1(CD274) on tumour cells and in the microenvironment of DLBCL and related neoplasms." (PMID 26362649, 2015). "Of those, clusters 10 and 8 mapped to the lower and higher “activation bridges” on the UMAP space, respectively, and expressed higher level of Cd274 and Cd40, suggesting that they might represent endpoint activated cDC1 states in tumours, while clusters 7 and 9 may correspond to transitional states." (PMID 40745918, 2025). "Compared to IMs, recMacs were enriched for canonical tumor-promoting transcripts including Spp1, Vegfa, Arg1, and Cd274 Together, these data suggest that while both populations contribute to immune regulation, recMacs are more transcriptionally aligned with tumor-promoting programs." (PMID 40630529, 2025). "The CD274 gene encodes programmed death ligand 1 (PD-L1), which not only exerts a suppressive influence on the immune system but also holds a unique tumor-intrinsic function in fostering tumor growth, facilitating metastasis and conferring resistance to therapeutic interventions." (PMID 40143965, 2025). "In addition, in breast cancer, CD274 expression was positively correlated with the infiltration of iTreg cells, cytotoxic T cells, and Th1 cells (among others), and negatively correlated with the infiltration of neutrophils in this tumor." (PMID 39796650, 2024). "We evaluated the tumor immune landscape through the CIBERSORT algorithm, which indicated the upregulation of resting Myeloid Dendritic Cells (DCs), memory B cells, and naïve B cells and high expression of key immune checkpoint molecules (CD274 and PDCD1LG2) in the high-risk group." (PMID 38310291, 2024).
tumor (continued). "Besides being an immune checkpoint molecule and preventing anti-tumor T cell response, PD-L1 (B7-H1, CD274) has a cancer cell-intrinsic pro-survival function and may contribute to cancer chemoresistance." (PMID 39696697, 2024). "Moreover, augmenting miR-4429 levels led to a considerable reduction in CD274 expression and subsequent restraint of the PI3K/AKT signalling pathway, signifying the tumour-suppressive potential of miR-4429 in ccRCC through its targeting of CD274 and control over the PI3K/AKT pathway." (PMID 38802631, 2024). "Additionally, LAMP3+ DCs in tumor tissues showed higher levels of CD274 compared to those in normal tissues, suggesting that LAMP3+ DCs infiltrating the tumor region could directly inhibit CD8+ T cells or attract Tregs to the tumor area." (PMID 38552055, 2024). "Tumor-mediated bypass of immune checkpoint inhibitor (ICI) therapy with anti-programmed death-1 (PD-1), anti-programmed death-ligand 1 (PD-L1, also called B7–H1 or CD274) or anti-cytotoxic T lymphocyte associated antigen-4 (CTLA-4) is a challenge of current years in the area of cancer immunotherapy." (PMID 38144305, 2023). "Among the pro-tumor effects, IFNG can lead to recruitment of suppressive cells like regulatory T cells or myeloid-derived suppressor cells (MDSCs) or induce expression of immune checkpoint ligands like programmed death-ligand 1CD274 (common alias: PD-L1, encoded by the Cd274 gene) on tumor cells." (PMID 37182110, 2023). "Also, critical immune checkpoint genes such as LAG3, PDCD1LG2, CD274, IDO1, PDCD1, and CTLA4 were evaluated because these genes are activated when T cells identify and attach to associated proteins on other cells, such as certain tumor cells." (PMID 37876438, 2023). "A study revealed that the CD274 (PD-L1) gene could stimulate the immune escape of tumor cells." (PMID 37730847, 2023). "Current CD274 mutation detection usually needs tumor tissues from patients, which limits concomitant diagnosis and precise drug guidance for patients with no access to tumor tissue." (PMID 36717553, 2023). "The mIF results suggest that SV in CD274 could promote the immune escape behavior of tumor cells." (PMID 36717553, 2023). "Similarly, IHC (Immunohistochemistry) quantified PD-L1 (CD274) expression, microsatellite instability, and Tumor Mutation Burden (TMB) have been used in clinical settings to assess whether NSCLC patients could benefit from Immune Checkpoint Inhibitor (ICIs)." (PMID 38148837, 2023). "Mutation in the 3' UTR region of CD274 gene has been recently reported in hematologic and solid tumors as a potential biomarker for assessing efficacy during immunotherapy, suggesting the rare variants in the UTR region of CD274 gene to guide tumor immunotherapy." (PMID 36717553, 2023). "However, depending on the tumor sample growth pattern, the expression of CD274 changes." (PMID 37370832, 2023). "However, tumor cells could upregulate the expression of CD274 to exert negative regulatory effects and blunt the anti-tumor function of T cells." (PMID 37629061, 2023). "In addition, the tumor marker CD274 (PD-L1) was found on spheroid cells." (PMID 36142766, 2022). "The evasion of tumor cells from immunorecognition was associated with elevated expression of immune checkpoint molecules such as programmed cell death-1 (PD-1, CD279), its ligand PD-L1 (CD274), cytotoxic T-lymphocyte associated protein-4 (CTLA-4, CD152), or the cell surface molecule B7-H3 (CD276)." (PMID 35628262, 2022). "We observed that heat-iMVA in PRC2-loss murine tumor cells (AT3 [sgEed], SKP605 [sgEed]) not only triggered type I IFN production (e.g., Ifnb1 and Ifna4), but also rescued the PRC2-loss–mediated IFN-γ signaling deficiency, resulting in increased chemokines and Cd274 (Pdl1) expression." (PMID 35852856, 2022).
tumor (continued). "Previous study found impaired PINK1 and PRKN expression could promote the degradation of SLC25A37 and SLC25A28 and increase the mitochondrial iron accumulation, which lead to AIM2-mediated HMGB1 release that further induced expression of CD274/PD-L1 in tumor cells." (PMID 36612054, 2022). "For instance, tumor/adjacent confined suppressive dendritic cells (i.e., DC subcluster 5) have been identified as a subset of dendritic cells (c21) with high expression of CD274, LAMP3, and CCL22, which may negatively regulate immune cells." (PMID 36333338, 2022). "Individual markers such as CD274 (PD-L1) (P = 0.04) and CTLA4 (P = 0.01) as well as signatures associated with effector cell types such as activated CD8 T cells (P = 0.05) and NK cells (P = 0.05) were also significantly elevated in responders based upon pretreatment tumor samples." (PMID 36923304, 2022). "Furthermore, we discovered that L1CAM was linked to immune cell infiltration and ICG (CD274, LAG3, PDCD1LG2, CTLA4), and we hypothesized that L1CAM may have a regulatory role in the tumor microenvironment, influencing tumor growth and metastasis." (PMID 36212450, 2022). "Moreover, we found that DDC expression significantly correlated with an immunosuppressive tumor microenvironment, higher intra-tumoral heterogeneity, elevated expression of immune checkpoint CD274, and possibly mediated malignant behaviors of ccRCC cells via the PI3k/Akt signaling pathway." (PMID 36544704, 2022). "However, on account of lack of targeted gene mutations, low PD-L1 (CD274) expression rate, and resistance after targeted therapy, there are still a significant proportion of patients making a tumor progression and die." (PMID 35833114, 2022). "After further analysis, C10-Tumor-INHBA and C04-Tumor-CXCL10 had enriched the highest level of cell death signaling, while the highest expression of CD274 (encoding PD-L1) was in C10 and C00, implying a limited correlation between tumor CD274 expression and tumor cell death." (PMID 33754038, 2021). "Interestingly, Pd-l1 (Cd274) was also upregulated, consistent with the induction of adaptive immune resistance mechanisms following local immune activation and anti-tumor immunity." (PMID 34445452, 2021). "Cancer cells expressing CD274 may affect regulatory T cells in the tumor microenvironment." (PMID 35280928, 2021). "There is evidence that T cells lose their effector function and ability to kill tumor cells when stimulated by tumor antigens, which may be due to the increasing diversity and number of inhibitory receptors, including CD274, PDCD1LG2, HAVCR2, CTLA4, LAG3, PDCD1, TIGIT." (PMID 33592580, 2021). "Since the primary function of coinhibitory receptor/ligand pairs is to attenuate the magnitude and duration of immune responses in order to minimize collateral tissue damage during a host immune response, PD-L1/CD274 expression of antigen-presenting cells might contribute to tumor escape." (PMID 33066260, 2020). "Programmed death ligand-1 (PD-L1, CD274, and B7-H1), which is a transmembrane glycoprotein expressed mainly on antigen presenting cells (APCs) and tumor cells, inhibits activated T-cells by binding to their inhibitory receptor, PD-1, in the tumor microenvironment." (PMID 32123492, 2020). "Interestingly, the macrophage populations lacked Cd274 (PD-L1), which has been described in tumor-associated macrophages (TAMs)." (PMID 33072601, 2020). "Furthermore, ROCKi+anti-PD-1 decreased levels of PD-1 ligand (CD274, best known as PD-L1) in both tumor cells and CD206+ macrophages, which could contribute to enhanced anti-PD-1 efficacy." (PMID 32391428, 2020). "In particular, the anti-tumor effects observed after monoclonal antibody (mAb)-mediated the blockade of the ICPs; cytotoxic T lymphocyte associated protein-4 (CTLA-4, CD152), programmed death-1 (PD-1, CD279) and its ligand PD-L1 (CD274, B7-H1), revolutionized the field of immuno-oncology." (PMID 33374804, 2020).